IL10 (interleukin 10)
Diseases named in the same sentence as IL10 in open-access papers (continued):
Sharing a sentence is not in itself a finding about the gene and the disease.
tumor (continued). "In multiple murine tumor models, treatment with the peritumoral administration of half-life-extended interleukin-10–Fc fusion protein promoted the expansion of terminally exhausted CD8+ TILs and promoted the effector function and enhancing oxidative phosphorylation in these exhausted T cells." (PMID 35203357, 2022). "IL-10, as a multifunctional cytokine, leads to promotion of tumor proliferation and metastasis." (PMID 36544523, 2022). "For some degree of consistency, Bregs can be defined functionally based on their ability to produce suppressive and anti-inflammatory cytokines (IL-10, TGFβ, and IL-35) that suppress pro-inflammatory or cytotoxic anti-tumour cells, and we have used this format to describe Bregs in a cancer setting." (PMID 35350071, 2022). "Also in HCC, CD27+ Bregs present in the tumor microenvironment cause the decrease and dysfunction of CD8+ T cells through IL-10 production, and their level is correlated with the disease stage and early recurrence." (PMID 36618354, 2022). "Moreover, this is associated with polarization towards M2 macrophages, which predominate among the TAMs in the tumor environment and secrete large amounts of IL-10 and TGF-β." (PMID 35372586, 2022). "In mechanism, obese adipose tissue is regarded as chronically inflammation tissues, through expressing inflammatory cytokines such as IL-1beta, IL-6, IL-10, and TNF-alpha, cancer-associated obese adipocyte recruits macrophages, neutrophils and other immune cells into tumour microenvironment." (PMID 35296087, 2022). "Therefore, the roles of IL-10 on tumor development are dependent on the local environment and physiopathological states." (PMID 35784354, 2022). "The interaction of PD-1/PD-L1 in the tumor microenvironment can promote T cell dysfunction, failure, apoptosis, neutralization, and the formation of IL-10, thus enhancing the proliferation and survival of tumor cells to promote the development and progression of cancer." (PMID 35370736, 2022). "Furthermore, high tumor expression of IL-10 and IL-4 resulted in lower recurrence free survival (p = 0.000 for IL-10; p = 0.021 for IL-4)." (PMID 35255925, 2022). "Supporting this hypothesis, the Th2 regulators, Interleukin-4 (IL4) and 13 (IL13), as well as IL10, have been demonstrated to play important roles during primary tumor progression in mouse models of cancer." (PMID 36077870, 2022). "Tumor cells secrete IL-10, TGF-β and other immunosuppressive molecules." (PMID 35493517, 2022). "STAT3 activation contributes to a highly immunosuppressive tumor microenvironment due to increased secretion of IL-10 and TGFβ, negative regulation of neutrophils, NK cells, effector T cells, and DCs and positive regulation of Treg cells and myeloid-derived suppressor cells (MDSCs)." (PMID 36614001, 2022). "Previously, we demonstrated that intratumoural injection with caerin 1.1/1.9 (caerin) significantly increases the survival time of TC-1 tumour bearing mice treated with HPV16 peptides/monophosphoryl lipid A/anti-IL-10 and anti-PD-1 therapy (Double-therapy, DT)." (PMID 36497272, 2022). "In addition, KRT17 can activate different macrophage populations and subtypes (such as M1 and M2) through interferon γ, tumor necrosis factor-α and interleukin 10, which play an important role in tumor proliferation and differentiation." (PMID 35646078, 2022). "Importantly, PGE2 blockade in vivo normalized IL12 expression to vehicle levels, while decreasing IL10 expression in tumor DCs (respectively)." (PMID 35347124, 2022). "Importantly, IL-10 is a multifunctional cytokine that regulates cell growth and differentiation, immune response, and tumor development, particularly in hematopoietic neoplasms." (PMID 35914074, 2022). "IL-10 secretion in HL can suppresses Th1 responses that could promote the antitumor response and high IL-10 receptor in tumor cells was seen in EBV lymphomagenesis." (PMID 36035394, 2022).
tumor (continued). "At first, the expression of inflammatory factors IL-6, TNF-α and IL-10 is increased, suggesting that HCC cells may induce Mφs to trend towards tumor-associated macrophages (TAMs), thus promoting disease progression." (PMID 36032078, 2022). "Our IPA and GO analyses further showed that in the tumor infiltrating CD11b+ cells, several tumor promoting and immune suppressive pathways are enriched and mobilized, including ‘tumor microenvironment pathway’, IL-10/IL-4/TGFb signaling, T cell exhaustion pathway." (PMID 36439171, 2022). "Therapeutic vaccines incorporating a cytokine, an interleukin-10 signaling inhibitor, drastically increase vaccine-induced antigen-specific T cell responses, attracting more T cells to the tumor site, and furthermore prolong the survival time of tumor-bearing mice." (PMID 35445137, 2022). "The IL‐10 expression levels were declined in the miR‐192‐5p antagomir tumours." (PMID 35969010, 2022). "The mechanism driving IL-10 gene expression in tumor cells is not yet fully understood." (PMID 35255925, 2022). "In addition, IL-10 can stimulate T and B lymphocytes, and IL-10 can also stimulate T and B lymphocytes in patients with tumor." (PMID 36081511, 2022). "A multicenter phase 1 clinical trial for PEGylated IL-10 monotherapy and combination therapy with anti-PD-1 also demonstrated expansion of antigen experienced CD8+ T cells in advanced tumor patients in both groups, further supporting an activating role for IL-10 in tumor immunity." (PMID 36248808, 2022). "Additionally, pDCs‐infiltrating gastric cancer and breast cancer are found to support tumor progress by promoting Treg and Th2 cell differentiation and IL‐10, IL‐5, and IL‐13 secretion." (PMID 34964283, 2022). "In order to test whether this photodynamic chemotherapy could mediate the immune response in tumor site, we measured the mRNA expression level of Il-2, Il-6, Il-10, Tnf-α, Tgf-β and Inf-γ in tumor issues." (PMID 35999549, 2022). "In tumor background, including TETs, the most abundant B-cell population displays a regulatory phenotype, termed as B10 cells, due to the secretion of immunosuppressive cytokine interleukin-10 (IL-10)." (PMID 35887212, 2022). "Expression of CD73 on tumor-infiltrating NK cells is low, as we and others have shown, but CD73+ NK cells were associated with a hyper-functional phenotype, including the ability to produce IL-10." (PMID 35815945, 2022). "The research shows that the PD-L1 expression of DCs is upregulated after IL-10 treatment, which may be the mechanism of immune tolerance in the tumor microenvironment." (PMID 35178106, 2022). "At the time of tumor formation, it stimulates the death of cancer cells, but for cancer cells that have escaped from the control of the host’s immune system, IL-10 may be a strong cancer promoter." (PMID 36289922, 2022). "GNB4 expression was notably related to the tumor-associated macrophage (TAM) markers CCL2 (Cor = 0.527, P = 1.64e−28), IL10 (Cor = 0.61, P = 5.02e−40), M2 macrophage marker CD163 (Cor = 0.66, P = 1.01e−48), VSIG4 (Cor = 0.64, P = 5.17e−45), and MS4A4A (Cor = 0.723, P = 1.26e−62)." (PMID 35756485, 2022). "The fact that FBL-3 tumor cells are controlled in spite of their Env expression and that Env DNA immunization leads to impaired control suggests that the expression levels determine the degree of IL-10 induction and suppression of CD8+ T-cell induction." (PMID 36605206, 2022). "Conversely, M2 macrophages are identified by their ability to suppress anti-tumor responses by producing IL-10 and TGFβ, recruiting Tregs and Th2 cells, supporting fibrosis to exclude CTLs, sequestering L-arginine through Arginase-1 (Arg-1), and expressing immune checkpoint molecules." (PMID 36248881, 2022).
tumor (continued). "Tumors can eventually overcome antitumor immunity through mechanisms already mentioned, including tumor antigen editing, loss of MHC I expression, and expression of immune inhibitors such as PD-L1 or suppressive mediators such as IL-10, TGF-β, and TRAIL decoy receptors." (PMID 36612080, 2022). "However, IL-10 has recently been reported to enhance the anti-tumor effects of CD8+ T cells directly and indirectly." (PMID 36238278, 2022). "Furthermore, CD163+ functional TAMs can be developed in tumor-bearing IL-6 transgenic mice and have produced high levels of immunosuppressive molecules, such as arginase-1 (Arg-1), IL-10, and VEGF." (PMID 35740551, 2022). "Adenosines cause the expression of IL-10 and VEGF, leading to angiogenesis and tumor progression." (PMID 35205204, 2022). "CSCs can not only transform into cancer cells and enhance their resistance to chemoradiotherapy, but also secrete immunosuppressive cytokines such as transforming growth factor-β (TGF-β), interleukin-6 (IL-6), IL-10, and IL-13, which can induce immune evasion of tumor cells." (PMID 36176299, 2022). "Besides tumor cells, other immune cells are also IL-10 producers in the TME, including MDSC, TAMs, and regulatory T cells, that contribute to an autocrine- and paracrine-induced immunosuppressive environment." (PMID 36310582, 2022). "One study showed that patients with advanced GC have elevated levels of circulating IL-10 and TGF-β (these may be both tumor- and M2 macrophage-secreted), which is associated with decreased NK cell cytotoxicity." (PMID 36497422, 2022). "We note that HNSCC can promote Th2-skewed response by regulating IL-10 expression and secretion in the tumor microenvironment and that IL-10 has been shown to inhibit IFN-α production in HNSCC, which may lead to antitumor poor therapeutic efficacy." (PMID 36406133, 2022). "IL-10 release catalyses an immune response that inhibits tumor growth." (PMID 35445056, 2022). "Decreased infiltration of the tumor by CD4+ and CD8+ T cells and the increased presence of regulatory T cells as well as TH2 cytokines (IL [interleukin]-4, IL-5), transforming growth factor (TGF)-β, and IL-10, also lead to an immunosuppressive environment in the tumor." (PMID 36230474, 2022). "In addition to tumor cells, these cells produce growth factors, chemokines, and local cytokines, such as IL-10, VEGF, TGF-β, and IL-4 which stimulate tumor growth and proliferation." (PMID 36153626, 2022). "In addition, promoted BHLHE40 switches off the IL-10 inflammatory “brake” and stimulates the proliferation of (tumor) tissue-infiltrating lymphocytes and inhibits antiviral THαβ cells, which are driven by IL-10 and IFNα/β." (PMID 35723340, 2022). "Strikingly, PARP inhibition can mitigate the M2-inducing effects of IL-4, IL-10, and M-CSF and results in large, highly phagocytic macrophages with remarkable anti-tumor activity ex vivo, suggestive of direct reprogramming of tumor macrophages by PARP inhibition." (PMID 36223740, 2022). "Besides, it has been reported that tumor cells secreted the immunosuppressive molecules, such as IL-10 and TGF-β, inhibited the maturation of DCs and increased the production of Tregs." (PMID 35236203, 2022). "For example, upon the high levels of tumor-derived lactate, high-expressed PD-L1 on the surface of tumor cells, or IL-4, IL-10, and TGF-β are present in TME, tumor-associated macrophages (TAMs) would polarize into the M2 phenotype, which plays a pro-tumor role." (PMID 36246629, 2022). "There was a significant increase in secreted IL-10 protein in tumor cells co-cultured with B cells." (PMID 35255925, 2022). "IL-10 also reduces the anti-tumor activity of T cells and NK cells, thus promoting tumor growth." (PMID 35205842, 2022). "Similarly, macrophage-synthesized IL10 inhibits antitumoral cytotoxic T-cell responses, thereby promoting tumor progression." (PMID 36077870, 2022). "Accordingly, lymphoma tumor cells can increase IL-10 secretion to produce CD40L by T cells." (PMID 35326620, 2022).
tumor (continued). "In addition, in HCC, CD27+ expressing Bregs has also been reported to suppress T cell anti-tumor immunity and promote tumor progression through IL-10 secretion and PD-1 expression." (PMID 36618354, 2022). "IL-10 was originally considered an anti-inflammatory cytokine, and its role in tumor pathogenesis and development is extremely controversial as it exhibits both anti-tumor and tumor promotion characteristics." (PMID 35470375, 2022). "The shift in cytokine production has a dual effect on the tumor microenvironment with the decrease in IL-10 production relieving IL-10-mediated suppression of DC function, and the increase in IL-12 production driving cytotoxic T lymphocyte-activating Th1 responses." (PMID 35740589, 2022). "For instance, hypoxia induces the expression of the high-mobility group B1 (HMGB1) in the tumor cell-released autophagosomes (TRAPs), which in turn induce IL-10 production in B cells, with a consequent suppression of T cell function and thus protection for tumors against immune response." (PMID 35565420, 2022). "IL-10 acts to promote tumor growth through the JAK2/STAT3 pathway." (PMID 36338705, 2022). "Furthermore, after adjustments of tumor stage, age, race, gender and tumor purity, under low expression of IL10, higher macrophage levels intended to show a worse prognosis of HCC." (PMID 35637248, 2022). "The tumor microenvironment is characterized by high levels of IL-10 and MDSCs are the principal producers of this cytokine IL-10, in turn, strengthens the immunosuppressive ability of MDSCs in a vicious cycle, by upregulating the expression of different immunosuppressive molecules." (PMID 35757002, 2022). "Many tumor-producing factors that are critical for tumor growth and immunosuppression, such as IL-6, IL-10 and VEGF, activate STAT3 to create an efficient “feedforward” mechanism to ensure increased STAT3 activity both in tumor cells and in tumor-associated immune cells." (PMID 34875483, 2022). "TAMs from SphK2-deficient tumors displayed a pronounced anti-tumor phenotype, showing an increased expression of the pro-inflammatory markers/mediators such as NO, TNF-α, IL-12 and MHCII and a low expression of anti-inflammatory IL-10 and CD206." (PMID 35756630, 2022). "Monocyte count can be used as a predictor, possibly because monocytes may have protumor effects by recruiting neutrophils to the tumor microenvironment by secreting interleukin-10 (IL-10) to achieve immunosuppressive effects." (PMID 35721326, 2022). "In sum, these studies suggest that TAM-associated tumor cell proliferation occurs in an IL-6 or IL-10/STAT3 signal cascade dependent manner and targeting proteins in the IL-6 or IL-10/STAT3 signaling pathway to attenuate tumor cell proliferation is promising in anti-tumor therapies." (PMID 35327584, 2022). "In lean subjects, the population of immune cells (particularly macrophages and iNKT cells) seem to maintain ‘immune surveillance’; they are able to detect and kill potential tumour cells while producing cytokines (e.g. IL-10) which attract and maintain this population." (PMID 36038791, 2022). "Additionally, ICOS contributes to anti-tumor T cell responses and graft-versus-host disease by reinforcing expression of various Th1 and Th2 cytokines such as IL-4, IL-10, IL-21 and IFN-γ." (PMID 36139142, 2022). "IL‐10, for instance, can take pro‐ or anti‐tumor activities." (PMID 35301813, 2022). "IL-10 may be involved in the suppression of tumor-promoting inflammatory mediators and the regulation of tumor angiogenesis." (PMID 35204188, 2022). "In addition, a recent study found that γ-Aminobutyric acid (GABA) derived from B cells promotes tumor growth by facilitating IL10+ macrophages in TME." (PMID 36033455, 2022). "TAMs themselves secrete IL-6, IL-8, and IL-10 that promote tumor growth." (PMID 35892729, 2022).
tumor (continued). "In addition, the increased IL-2 and decreased IL-10 levels following SIT treatment suggest that SIT can also achieve anti-tumor effects by increasing the production of anti-tumor cytokines and reducing the release of immunosuppressive factors in the body." (PMID 35756648, 2022). "In this study, it was observed that IL-10 blockade could increase the capacity of our adjuvant E7&IL-24 vaccine in eradicating tumor cells, which was further proved by an increase in the level of IFN-γ and caspase-9." (PMID 35752792, 2022). "Along with monocyte chemotaxis to the tumor niche, HCMV-encoded IL-10, which appears to mimic the immunomodulatory effects of human IL-10, shifts monocyte polarization toward a deactivated pro-tumoral M2c phenotype, limiting CD4+ T cell activation and proliferation substantially." (PMID 35515137, 2022). "Tumor cell-released autophagosomes polarize monocytes to an M2-like phenotype that possesses an elevated expression of PD-L1, IL-10, and CD163, but reduced expression of the MHC II cell surface receptor HLA-DR (human leukocyte antigen—DR) with T cell-suppressive functions." (PMID 36233088, 2022). "Tumor-associated macrophages and MDSCs are usually the main myeloid cell populations in aggravated TME and constitute the key producers of suppressive TGF-β and IL-10 that promote NK cell dysfunction." (PMID 36233088, 2022). "In vivo, a dose of 3 μg nanobody per gram of body weight in tumor‐bearing mice could attenuate tumor progression and suppress excessive circulating levels of IL‐1a, IL‐2, IL‐10, IL‐12, and IL‐17A pro‐inflammatory cytokines." (PMID 34694686, 2022). "IL-10 is found to be overexpressed in TCs and its expression was shown to be correlated with tumor size and tumor extension, suggesting that IL-10 might enhance the function of tumor progression." (PMID 35479325, 2022). "In addition, IGF2R has been shown to promote the secretion of IL-10 by B cells, and IL-10 directly activates or expands T cells in a tumor." (PMID 36330486, 2022). "In addition, the tumor releases the IL-6, IL-10, VEGF, gangliosides, and/or macrophage colony-stimulating factor (M-CSF), thus suppressing DC activity and differentiation both in vivo and in vitro." (PMID 35883508, 2022). "Numerous studies show that, within the tumor microenvironment, STAT3 signaling induces pro-carcinogenic cytokines (such as IL-6, IL-10, and IL-23) and inhibits anti-carcinogenic cytokines (e.g., IL-12), thereby promoting tumor immune evasion and cancer progression." (PMID 36557902, 2022). "As we detected elevated IL-10 levels in primary tumor cells expressing PDGFRβ, we hypothesized that overexpressed PDGFRβ might additionally fuel STAT3 activity in ALCL." (PMID 36045346, 2022). "Initially, IL-10 production was mainly attributed to Th2 lymphocytes, but further studies have demonstrated that B cells, T cells, macrophages, as well as cells not directly involved in the cellular response, such as keratinocytes, and tumor cells can be sources of IL-10." (PMID 35805112, 2022). "Whereas IL-10 inhibit LCs migration, IL-1β contribute to their proliferation and their pro-tumourigenic cytokine network is stimulated leading to tumour pathogenesis through the dysregulation of signalling pathways in human dysplastic oral keratinocytes (DOK), as demonstrated in OSCC cells." (PMID 35406451, 2022). "And GABA produced by B cells in TME impairs tumor growth by supporting IL-10+ macrophages." (PMID 36033455, 2022). "Indeed, SCID mice subcutaneously injected with IL-10 transfected B-cells lymphoma DG75 showed a reduced tumor development in comparison with normal cells." (PMID 35626056, 2022). "Notably, SCT treatment slightly decreased CD3+ cell fraction and increased IL‐4+ and IL‐10+ CD4+ T cell populations in the tumor‐infiltrating T cells." (PMID 34747157, 2022).